PRL (prolactin)
Diseases named in the same sentence as PRL in open-access papers (continued):
Sharing a sentence is not in itself a finding about the gene and the disease.
migraine (continued). "A preclinical study seeking to dive more deeply into the sex × stress clinical observations interrogated the relationship between the hormone prolactin and migraine response." (PMID 40634879, 2025). "Hormonal activity within the pituitary–hypothalamic axis plays a critical role in triggering migraine attacks, and prolactin, a 199-amino-acid peptide secreted by lactotroph cells in the anterior pituitary gland, is regulated by dopamine." (PMID 40699640, 2025). "Taken together, these findings support a pathophysiological and therapeutic role for prolactin and dopamine signaling in migraine." (PMID 41052788, 2025). "Previous studies have shown a role for prolactin in animal migraine models induced by either stimulation of the dura mater or repeated stress exposure." (PMID 41436934, 2025). "Elevated serum prolactin levels have been reported in individuals with migraine across multiple clinical studies." (PMID 41052788, 2025). "This review examines the role of dopamine and prolactin in migraine pathophysiology, with special emphasis on potential clinical therapeutic implications." (PMID 41052788, 2025). "Prolactin increases release of calcitonin gene-related peptide (CGRP), a neuropeptide that is causal in many people with migraine." (PMID 38658853, 2024). "Estrogen and stress-related influences on prolactin are therefore likely to have a CGRP component in promoting migraine attacks in women." (PMID 38658853, 2024). "Recent work has also highlighted the role of prolactin, a circulating neurohormone that is released by the pituitary and that can also be produced locally by multiple cell types, in promoting migraine-like pain." (PMID 38658853, 2024). "The female selectivity of PRL in promoting migraine-like pain behavior was confirmed by direct dural application in rodents." (PMID 38658853, 2024). "Clinical and preclinical studies have supported the involvement of PRL and its receptors in migraine, with important sex differences." (PMID 38397400, 2024). "In both mice and rats administered prolactin durally, a prolonged effect of facial hypersensitivity was observed in in female animals only, and meningeal prolactin blockade reduced the migraine-like responses induced by durally administered CGRP." (PMID 38481473, 2024). "To gain insight into the role of OT and PRL in migraine pathophysiology, we have focused on their effects on pain modulation." (PMID 36967387, 2023). "Clinical and preclinical studies report a pronociceptive role of PRL as a sensitising factor for pain-related structures also in the trigeminovascular system, which has specific relevance for migraine." (PMID 36967387, 2023). "The evidence suggests that it is necessary to determine the exact role of prolactin in the pathogenesis of migraine with the use of well‐designed studies having sufficient sample sizes." (PMID 37190874, 2023). "A correlation between high prolactin and migraine was recently described in which administration of the dopamine D2 receptor antagonist cabergoline proved effective in reducing intense, unilateral face pain involved in prolactinoma-associated headache." (PMID 37795389, 2023). "In this respect, clinical studies have shown that high levels of PRL are associated with the progression of migraine, therefore, PRL is considered as a worsening factor for migraine." (PMID 36967387, 2023). "Prolactin, which has a crucial role in controlling the hypothalamus-pituitary-gonadal (HPG) axis, seems to be involved in signaling mechanisms underlying migraine." (PMID 38112066, 2023). "A meta-analysis from 2019 showed higher PRL levels in the migraine patient group compared to controls based on 13 studies, although there was a high degree of heterogeneity among studies." (PMID 36967387, 2023). "For this reason, the authors of the review decided to investigate the link between the pathophysiology of migraine and two hormones: PRL and OT." (PMID 36967387, 2023).
migraine (continued). "Preclinical studies have shown that PRL contributes to the pathogenesis of migraine involving sex-specific mechanisms." (PMID 36967387, 2023). "Studies have revealed changes in serum prolactin (PRL) levels in relation to migraine, although the results have been inconsistent." (PMID 37190874, 2023). "In recent years, preclinical research on the link between PRL and migraine also improved our understanding of sex-related characteristics of migraine." (PMID 36967387, 2023). "Treatment of the microadenoma with bromocriptine provided complete and lasting resolution of the migraine as well, suggesting a possible etiologic relationship and prospect regarding dopamine agonist treatment in such cases of migraine influenced by prolactin." (PMID 38112066, 2023). "Although studies evaluating prolactin levels in subjects with migraines have shown different results, taken as a whole, our results on the levels of prolactin in migraineurs compared to controls appear to be corroborated by previous evidence in this field." (PMID 37190874, 2023). "Previous studies showed that drugs such as bromocriptine and methysergide, which affect PRL levels, are effective in the prevention of migraine, presumably by interacting with dopamine and 5-HT receptors." (PMID 36967387, 2023). "Overall, considerable evidence supports the link between elevated levels of endogenous prolactin, its receptors, and the increased incidence and severity of migraine." (PMID 38112066, 2023). "In the present study, subjects with chronic and episodic migraine during the ictal phase were shown to have higher serum levels of prolactin than the episodic migraineurs in the interictal phase and age‐ and sex‐matched headache‐free individuals." (PMID 37190874, 2023). "Following this rationale, treatments targeting PRL nociception should specifically target the PRLR in certain migraine pain-related structures, such as the cranial trigeminal system." (PMID 36967387, 2023). "In conclusion, there is clear evidence that PRL signalling plays an important role in pain pathways, including migraine." (PMID 36967387, 2023). "The link between migraine and PRL also becomes evident when taking into account that the normalisation of PRL levels can alleviate headache (i.e., through PRL-decreasing medication, such as 0.5 mg of cabergoline twice a week)." (PMID 36967387, 2023). "The plasma levels of LH, FSH, and prolactin were similar between women with migraine and controls and were unaffected by the prophylactic treatment with dihydroergotamine." (PMID 38112066, 2023). "We describe the physiological role of prolactin and oxytocin, its relationship to migraine and pain, and potential therapies targeting these hormones or their receptors." (PMID 36967387, 2023). "Additional randomized and placebo-controlled clinical trials focusing on prolactin signaling are necessary to provide further insight into the role of prolactin in initiating migraine attacks and its future position in migraine treatment." (PMID 38112066, 2023). "(2018) assessed serum different hormones related to female gonadal function including prolactin of migraineurs and analyzed the relationship between these hormone levels and migraine characteristics." (PMID 37190874, 2023). "Studies on PRL levels almost comprehensively indicate that this hormone is found at higher levels in migraine patients compared to healthy controls." (PMID 36967387, 2023). "In animal studies, PRL administered to the dura mater elicited migraine-like behaviour only in females, and PRLR was more abundant in the female sex in trigeminal neurons." (PMID 36967387, 2023). "Higher prolactin levels in individuals with migraine were found in earlier studies, with a female sex-dominant trend." (PMID 34737888, 2021). "One line of evidence supporting the view that prolactin plays a crucial role in the pathophysiology of migraine is an investigation of prolactin circulatory levels in migraine." (PMID 34737888, 2021).
migraine (continued). "Dopamine agonists including bromocriptine and carbidopa/levodopa have been used to successfully treat migraine resulting from high prolactin levels." (PMID 34737888, 2021). "The regulatory role of prolactin has been found in nervous system processes such as stress responses, anxiety, neurogenesis, orofacial pain and migraine." (PMID 34737888, 2021). "Some cases of migraines have been treated with bromocriptine, a D2 agonist that inhibits prolactin release." (PMID 34737888, 2021). "A systematic review followed by a meta-analysis summarized the available literature since the 1970s on prolactin blood levels in patients with migraine." (PMID 34737888, 2021). "This focused review examines the past and present of the link between prolactin and migraine, and presents open questions and directions for future experimental and clinical efforts." (PMID 34737888, 2021). "Prolactin levels follow a circadian rhythm, adjusted by the hypothalamus, which is also believed to be involved in the onset of migraines." (PMID 34737888, 2021). "The ultimate goal is to shape an overview toward considering sex-based treatments for migraine with highlighting the role of prolactin." (PMID 34737888, 2021). "This focused review examines the past and present of the link between prolactin and migraine, and presents current open questions and potential directions for future experimental and clinical efforts." (PMID 34737888, 2021). "It is also worthwhile to mention that considering multifunctional role of prolactin and comorbid conditions in migraine, how being at a certain age or under a single or multiple simultaneous conditions can change bodily responses." (PMID 34737888, 2021). "In another study, however, lower prolactin serum levels were found during the acute phase of migraine." (PMID 34737888, 2021). "For the meta-analysis, a random effects model (i.e., variance components model) was preformed and the findings demonstrated that the blood levels of prolactin were higher in patients with migraine compared with healthy controls." (PMID 34737888, 2021). "It is therefore suggested that next studies to broaden the investigation of hormones and to potentially include prolactin while studying migraine/headache/pain in this population." (PMID 34737888, 2021). "In our study, we found similar prolactin levels between the migraine and control groups during interictal period." (PMID 21331754, 2011). "In this study, we aimed to investigate the sCD40L, prolactin and hsCRP levels in migraine patients during interictal period and their relationship with migraine subtypes and attack frequency." (PMID 21331754, 2011). "When the migraine patients were subdivided according the attack frequency, sCD40L, hsCRP and prolactin levels were indifferent among the frequent (4 or more attacks/month) and seldom (less than 4 attacks/month) attack groups." (PMID 21331754, 2011). "In conclusion, prolactin and dopamine may modulate migraine via distinct but converging neuroendocrine pathways, which could represent targets for migraine prevention." (PMID 41052788, 2025). "Current evidence on prolactin levels in migraine patients remains inconclusive." (PMID 40699640, 2025). "Disrupting prolactin signaling in sensory neurons attenuates facial hypersensitivity in female, but not male mice, suggesting yet another female-specific mechanism by which stress exacerbates migraine-like phenotypes." (PMID 40634879, 2025). "In addition, moderately elevated prolactin levels are reported in patients with migraine, in whom uncontrolled dopamine agonist-induced prolactin lowering improves headache in a high proportion of patients." (PMID 40168298, 2025). "Excursions in serum prolactin are hypothesized to trigger menstrual migraine and preclinical data demonstrate prolactin induced migraine-like behaviours and increased excitability in trigeminal neurons in female rodents." (PMID 40168298, 2025).
migraine (continued). "In line with this, preclinical and clinical studies indicate a link between prolactin and migraine." (PMID 40168298, 2025). "Prolactin produces female-selective migraine-like pain behaviors in rodents and enhances the release of calcitonin gene-related peptide (CGRP), a neurotransmitter that is causal in promoting migraine in many patients." (PMID 38658853, 2024). "Prolactin, a female expressed sex-related hormone, has been shown to play a role in migraine." (PMID 38481473, 2024). "Additionally, a preclinical study showed dural administration of prolactin resulted in female-specific migraine-like behavior in both cycling and ovariectomized rodents." (PMID 39439003, 2024). "CGRP, like prolactin, produces female-selective migraine-like pain behaviors." (PMID 38658853, 2024). "The dural administration of prolactin-induced long-lasting migraine-like behaviors only in women." (PMID 38397400, 2024). "Prolactin (PRL) is another crucial hormone involved in migraine." (PMID 38397400, 2024). "We present a case of a 10-year-old patient with a history of autism spectrum disorder (ASD), attention-deficit/hyperactivity disorder (ADHD), and migraine headaches who was incidentally found to have elevated prolactin levels while taking amitriptyline for migraine prophylaxis." (PMID 38826982, 2024). "Prolactin, a pituitary-derived hormone, and oxytocin, a hypothalamic neuropeptide, have become the recent focus of research interest, since it appears that they interfere with the migraine onset and symptom development." (PMID 38256310, 2023). "It has been demonstrated that some migraine medications have an impact on PRL levels." (PMID 36967387, 2023). "Increased serum PRL levels have been described in patients with headaches, especially migraine." (PMID 36967387, 2023). "In addition, the literature to date describing roles of minor sex hormones including prolactin, luteinizing hormone, follicular stimulating hormone, and gonadotropin releasing hormone in migraine are presented." (PMID 37795389, 2023). "The present case‐control study assessed the serum level of prolactin in migraine patients." (PMID 37190874, 2023). "Moreover, differentially pattern levels have been found between controls and patients with migraine of the hypothalamic-tuberoinfundibular system (prolactin and growth hormone)." (PMID 36797674, 2023). "Overall, the preclinical studies point to a female-specific mechanism of PRL in migraine." (PMID 36967387, 2023). "Additionally, knockdown of PRL-L resulted in persisting nociceptive hypersensitivity perpetuated by spinal NMDA activity and enhanced glutamate neurotransmission which affirms the proposed role of PRL-L in abolishing prolactin-induced migraine mechanisms." (PMID 37795389, 2023). "Despite these, even normal levels of prolactin could contribute to the sensitization of trigeminal sensory neurons and migraine attacks." (PMID 37190874, 2023). "Considering that PRL and PRLR display a sex-dependent activity, PRL signalling might represent an important approach in understanding sexual dimorphism in the pathophysiology of pain and migraine." (PMID 36967387, 2023). "In this respect, preclinical studies have demonstrated that PRL contributes to migraine pathogenesis involving sex-specific mechanisms, which may help to understand the sex-related differences in migraine." (PMID 36967387, 2023). "In comparison, a few studies showed that reduced PRL levels accompany migraine attacks." (PMID 36967387, 2023). "To this end, we designed a study to assess serum prolactin levels in subjects with EM and CM and compared these levels with an age‐ and sex‐matched headache‐free control group to investigate the relationship between prolactin and migraine." (PMID 37190874, 2023). "The findings suggest that changes in prolactin levels are related to the pathogenesis of migraine attacks and may contribute to the progression of migraine headaches." (PMID 37190874, 2023).
migraine (continued). "Furthermore, it has been suggested that high PRL levels play a role in the chronification and progression of migraine." (PMID 36967387, 2023). "These increased levels of PRL can be related to dysregulation of the hypothalamic-pituitary axis and may contribute to the onset of migraine and/or migraine-like headache attacks." (PMID 36967387, 2023). "Changes in prolactin and oxytocin levels are closely related to pregnancy and symptom management; therefore, their potential use as agonists and antagonists creates a promising possibility for targeted migraine therapy." (PMID 38256310, 2023). "In addition, the pituitary-derived hormone prolactin and the hypothalamic neuropeptide oxytocin have been reported to play a modulating role in migraine and contribute to its sex-dependent differences." (PMID 36967387, 2023). "Further studies support the concept of a female-specific mechanism that links PRL and migraine." (PMID 36967387, 2023). "Stress is a significant, albeit complex, migraine trigger that might involve prolactin-induced sensitization of the hypothalamic-pituitary-adrenal (HPA) axis and reduced efficacy of the kappa-opioid receptor (KOR) system to alleviate trigeminal nociception." (PMID 37795389, 2023). "Regarding prolactin and migraine treatment, dopamine agonists including bromocriptine and carbidopa/levodopa have reportedly been effective in managing migraines supposedly triggered by elevated prolactin levels by inhibiting prolactin release." (PMID 38112066, 2023). "Much like estrogen, upregulated prolactin might contribute to migraine via sensitization of trigeminal nociceptive neurons." (PMID 37795389, 2023). "Therefore, migraine treatment targeting prolactin should aim to block its effects using prolactin receptor antagonists or monoclonal antibodies specifically acting at migraine-pain related structures." (PMID 36967387, 2023). "The fact that the levels of one of these hormones can affect secretion of the other should be taken into account when using them as a target for migraine treatment, especially considering that OT has antinociceptive effects, while PRL leads to a more pronociceptive response." (PMID 36967387, 2023). "Moreover, in migraine patients, higher levels of prolactin have been identified that were also responsive to drugs lowering the prolactin level." (PMID 34737888, 2021). "Besides in vitro studies, a few in vivo studies have also evaluated prolactin and its receptor isoforms in migraine models and collectively the outcomes support the proposed potential for migraine development as a predominantly female disorder." (PMID 34737888, 2021). "The focus of this review is migraine, but it is interesting to identify how different are orofacial pain conditions compared with other types of pains, for example low back pain, while the prolactin is being investigated." (PMID 34737888, 2021). "In this focused review, the current knowledge is presented and the directions where prolactin research in migraine may evolve are proposed." (PMID 34737888, 2021). "Sex and other hormones (e.g., oxytocin, and prolactin) may play a role in sexual dimorphic features of migraine." (PMID 34737888, 2021). "Historically, two lines of evidence have been presented that link prolactin and migraine." (PMID 34737888, 2021). "Moreover, some cases of migraine have been successfully treated by blocking pituitary PRL with the dopamine agonist—bromocriptine or carbidopa/levodopa." (PMID 30356882, 2018). "Our results are concordant with two other studies reporting normal prolactin levels in migraine." (PMID 21331754, 2011). "It was hypothesized that the increased dopaminergic activity is responsible from prodromal, clinical and postdromal symptoms and, therefore, a decrease in prolactin levels should be expected during migraine attacks." (PMID 21331754, 2011).